HIF1A (hypoxia inducible factor 1 subunit alpha)
Diseases named in the same sentence as HIF1A in open-access papers (continued):
Sharing a sentence is not in itself a finding about the gene and the disease.
tumor (continued). "This hypoxia-mediated increase in HIF-1α promotes tumor progression through the HIF-1α−dependent activation of multiple genes, whose expression enables cancer cells to survive, metastasize, and acquire resistance to antiangiogenic therapy." (PMID 32080210, 2020). "Recently, it has been shown that conditional deletion of HIF-1α in NK cells inhibits tumor growth, the phenomenon dependent on elevated expression of activation markers, effector molecules and an enriched NF-κB pathway in tumor-infiltrating NK cells." (PMID 33260925, 2020). "The major regulator of the hypoxic response is the transcription factor hypoxia-inducible factor-1α (HIF-1α), and a previous study has shown that HIF-1α accumulates rapidly during CoCl2-stimulated hypoxia to induce a hypoxic-like response in tumor cells." (PMID 32091275, 2020). "Hypoxia, via the transcriptional machinery of HIF-1α, modulates the reprogramming of lipid metabolism, resulting in the support of fast tumor proliferation." (PMID 32751958, 2020). "A significant reduction of HIF1α-VEGF signaling axis within tumor by NLGP treatment has immense importance even from immunological perspective, where efficacy of NLGP is already proven." (PMID 32211322, 2020). "In end stages of tumor growth, the expression level of Hif1α, VEGFR1 and VEGFR2 were 22.42- (P < 0.001), 31.06- (P < 0.001) and 20.22-fold (P < 0.01), respectively." (PMID 32373503, 2020). "This axis accounts for stabilization of HIF-1α in normoxic conditions (pseudohypoxia), known to promote tumor formation, as described in ccRCC." (PMID 33233657, 2020). "Intratumoral injection of Cyr61 in HIF-1α-KD tumors revealed an in increased vessel permeability and tumor hypoxia." (PMID 33142239, 2020). "HIF-1α is a nuclear transcription factor that regulates the ability of tumor cells’ adaptation to hypoxia." (PMID 32796813, 2020). "HIF-1α also directly modulates immune cell activity in the tumor microenvironment to favor tumor growth and induces PD-L1 expression on tumor cells and immune cells; indirectly mediating immune escape and tumor progression." (PMID 33193345, 2020). "In sum, the activation of HIF-1α can be considered as a complex process, in which different tumor suppressor genes as well as various oncogenes are involved." (PMID 32846951, 2020). "HIF1A thus plays an indispensable role in tumor angiogenesis, and is a well-recognized marker in many cancers, including HCC." (PMID 32887289, 2020). "MA also reduces the cellular cytokines, such as NF-κB, COX2, matrix metalloproteinases (MMPs), urokinase-type plasminogen activator (uPA), and hypoxia inducible factor-1α (HIF-1α), which promote tumor growth and progression." (PMID 31991739, 2020). "Hif1a co-deletion completely abolished these tumour-promoting effects of Vhl deletion and these mice developed very few tumours, which grew slowly when they did develop." (PMID 32807776, 2020). "Taken together, these results demonstrated that miR-103a-3p promotes tumour glycolysis by regulating the Hippo/YAP1/HIF1A axis." (PMID 33218358, 2020). "It is evident that tumor adaptation to hypoxia is regulated by a balance between HIF1α and HIF2α, and alterations in the balance steer the HIF-regulated tumor-promoting processes." (PMID 32545251, 2020). "Of these three members, HIF-1α is frequently overexpressed in tumor cells, and is the most extensively studied in cancer research." (PMID 32631383, 2020). "Under physiological conditions, the tumor microenvironment is hypoxic; this is especially true of the central region of the tumor mass, where HIF-1α is overexpressed." (PMID 32883954, 2020). "HIF-1α can be used to predict tumor progression and the overexpression HIF-1α is correlated to poor survival in the clinical context." (PMID 32312328, 2020). "Depletion of SKP2 and HIF-1α attenuated Mint3-mediated tumor sphere formation ability and chemoresistance in AsPC-1 cells." (PMID 32826949, 2020).
tumor (continued). "TET1, as DNA demethylase, is thought to be associated with tumor metastasis, and hypoxia increases the expression of TET1 in a HIF-1α-dependent manner." (PMID 33109235, 2020). "Under hypoxia, the crosstalk between the HIF-1α, MMP-2, VEGF, and VEGFR-2 proteins has been associated with hypoxia-induced angiogenesis, leading to tumour progression and increased invasiveness." (PMID 33067558, 2020). "To investigate the effect of HIF-1α knockdown on tumor growth, we used a stable knockdown cell line produced by lentiviral transduction particles." (PMID 32847004, 2020). "Tumor cells in a hypoxic microenvironment activated the transcription of hypoxia inducible factor-1α (HIF-1α), which was used as transcription factors promote tumor invasion, metastasis and resistance to radiotherapy and chemotherapy." (PMID 32626528, 2020). "Activated HIF-1α in tumor cells can increase the expression and activity of glycolytic enzymes, including GLUT1 and HK2, to accelerate the glycolytic rate." (PMID 32454874, 2020). "When NIR was applied, Nb@IC-NPs can significantly relieve A549 cellular/tumor hypoxia by generating more reactive oxygen species (ROS), which in turn helps lower the expression level of HIF-1α." (PMID 33292202, 2020). "HIF-1α is overexpressed in hypoxic tumor tissues, including gastric cancer, and activates the transcription of many oncogenes, leading to the promotion of tumor growth." (PMID 33376737, 2020). "The CAIX and HIF1A expression, patients’ age, tumor characteristics, surgery status, and neoadjuvant chemotherapy drug classes were further involved in survival analyses for overall survival (OS) and progression-free survival (PFS)." (PMID 32212787, 2020). "HIF-1α is involved in tumor cell proliferation, angiogenesis, metastasis, and chemotherapy resistance." (PMID 32194804, 2020). "For several tumor-relevant gene products like Grp78, estrogen receptor alpha (ER-α), HIF-1α, or vimentin, IRES has been detected, suggesting that these proteins are synthesized under hypoxia." (PMID 32466213, 2020). "The expression of HIF-1α by tumor cells under hypoxic conditions is a well-known mechanism, and its role in tumor progression and metastasis is more and more characterized." (PMID 32344813, 2020). "It has been reported that HIF-1α, as nuclear transcription factor regulating tumor cells to adapt to anoxia, plays an important role in the regulation of tumor cell neo-vascularization." (PMID 32796813, 2020). "For instance it has been shown that BAY 87-2243, a potent inhibitor of HIF-1α, reduced tumor growth, potentially through targeting mitochondrial complex I (CI)." (PMID 32509579, 2020). "Elevated levels of hypoxia and hypoxia‐inducible factor 1α (HIF1α) in human sarcomas correlate with tumor progression and radiation resistance." (PMID 33047515, 2020). "Factors, such as hypoxia inducible factor 1α (HIF1α) within the tumor microenvironment also promote differentiation of MDSCs into TAMs, creating a feedback loop to support immunosuppression." (PMID 32983125, 2020). "Cinobufagin suppresses tumor neovascularization by altering the endothelial mTOR/HIF-1α pathway to trigger vascular endothelial cell apoptosis mediated by ROS, and it is emerging as a promising natural anti angiogenic agent." (PMID 32183342, 2020). "As we known, HIF-1α was a vital transcription factor, which contributed to tumor growth in many solid tumors, including CRC." (PMID 33244454, 2020). "HIF-1α plays an important role in the initiation and progression of tumour angiogenesis by controlling a variety of angiogenic elements." (PMID 33076322, 2020). "It was also reported that CCL5 promoted VEGF-dependent tumor angiogenesis in the human osteosarcoma microenvironment by activating the hypoxia-inducible factor (HIF)-1α signaling cascades." (PMID 32443699, 2020). "Recently, digoxin has also been used to treat tumor progression through the inhibition of HIF-1α synthesis." (PMID 32883954, 2020).
tumor (continued). "Hypoxia in the tumor followed by HIF-1α is one of the most important mechanisms to promote tumor progression and metastasis." (PMID 32152662, 2020). "In tumor-associated macrophages, aberrant Hif-1α activation and metabolic dysregulation by M-BKO contribute to an immunosuppressive tumor microenvironment." (PMID 32396064, 2020). "In the presence of O2, the hydroxylation of proline residues 402 and 564 of the HIF subunit HIF-1α enables the tumour-suppressor protein von Hippel–Lindau (VHL) to ubiquitinate HIF-1α, leading to its proteasomal degradation." (PMID 31819191, 2020). "Thrombin mediated-PAR1 activation signals through PI3K/AKT/mTORC1 and activates Hypoxia-Inducible Factor-1 alpha (HIF-1α), a well-known mediator of tumor survival, EMT, angiogenesis, and metastasis." (PMID 33365273, 2020). "Here, the authors use an intracranial injection mouse model and single-cell analysis of patient circulating tumour cells to demonstrate that increased hypoxic and HIF1A signalling promotes tumour growth in the brain." (PMID 33298946, 2020). "As a proof-of-principle approach, we show that DMM treatment blocks T-CM induced Hif-1α protein stabilization in vitro and suppresses tumor growth in vivo." (PMID 32396064, 2020). "In fact, PKM2 is highly expressed in tumor cells and LPS-stimulated macrophages, and the stabilization of HIF-1α favors the expression of IL-1β and glycolytic enzymes." (PMID 33374961, 2020). "According to the available evidence on glioblastoma, cells in the tumor periphery have low levels of HIF1α, low proliferation rate, and greater angiogenesis." (PMID 32660072, 2020). "HIF-1α is known as the most potent inducer of tumor angiogenesis that regulates the expression of proangiogenic factors, such as vascular endothelial growth factor (VEGF)." (PMID 32516967, 2020). "A previous study reported that tumor cell responses to hypoxia are predominantly mediated by HIF-1α, which transactivates more genes essential for adaptation and tumor survival." (PMID 32045997, 2020). "Malignant tumors grow quickly, resulting in poor oxygen supply to tumor tissues and activating HIF-1α overexpression." (PMID 33062005, 2020). "The least distinct differences in POX, PPARγ and HIF1-α expression were found in the group of highly differentiated tumours (G1, KI-67 < 40%)—The average expression of PRODH/POX and PPARγ was 88% compared to normal tissue, while HIF1α was 130%." (PMID 31935820, 2020). "Collectively, our findings demonstrate for the first time that compound 9 is a promising antiangiogenic agent targeting both VEGF/VEGFR2 signaling in ECs and HIF-1α/VEGF pathway in tumor cells." (PMID 32751120, 2020). "[18F]HX4 PET/CT was found to be a feasible non-invasive method to assess tumor hypoxia in 42 patients and correlated with HIF1α immunohistochemistry in matched surgical specimens." (PMID 33105540, 2020). "Finally, it is also noteworthy that HIF1A copy loss and HIF2A mRNA high tumours showed opposite effects on signatures for pericytes, endothelial cells and angiogenesis, implying that both HIF-1α and HIF-2α may act as positive factors that promote blood vessel formation in ccRCC tumours." (PMID 32807776, 2020). "It should however be noted that the magnitude of the z-scores are generally low, suggesting that this group of ccRCCs on average exhibits numerous subtle differences in immune inflammation compared to tumours with normal HIF1A copy number." (PMID 32807776, 2020). "HIF-1α plays a key role in the oxygen-sensing pathway and participates in the reprogramming of tumor metabolism." (PMID 32084009, 2020). "Hypoxia stimulates tumor angiogenesis and metastasis through up-regulating HIF-1α, followed by VEGF activation." (PMID 33245358, 2020). "We compared HIF1A loss and HIF2A gain tumours to diploid human ccRCCs and also took advantage of the wide distribution of mRNA expression levels of HIF2A to compare tumours in the top (Q4) and bottom (Q1) quartiles of HIF2A mRNA abundance." (PMID 32807776, 2020).
tumor (continued). "Tumors are frequently hypoxic and the activation of the hypoxia-inducible factor-1α (HIF1α) promotes tumor growth." (PMID 32825247, 2020). "HIF-1α appears to play a key role in this immunosuppressive process by driving the expression of cytokines that promote MDSC infiltration of the tumor mass." (PMID 35047983, 2020). "Specifically, hypoxia triggers the upregulation of PD-L1 in tumor cells in a HIF-1α-dependent manner, and HIF-1α accumulation in T cells has been suggested to favor differentiation into TH17 cells and to promote inflammatory diseases in humans." (PMID 32973789, 2020). "HIF-1α regulates a variety of tumor processes for adaptation, such as metabolism, erythropoiesis, angiogenesis, invasion, cell survival and proliferation." (PMID 32322559, 2020). "In addition to its central role as a pyruvate enzyme at cytoplasm, PKM2 may also translocate into the nucleus to function as a protein kinase and interact with many tumor-associated genes to accelerate carcinogenesis, including HIF-1α, Oct-4, STAT3 and beta-catenin 26,37-39." (PMID 32308748, 2020). "The expression level of MFAP5 and HIF-1α was remarkably correlated in same tumor species (r=0.493, P<0.01)." (PMID 32047565, 2020). "Deletion of HIF-1α in NK cells inhibits their ability to infiltrate tumor site and by increasing the VEGF availability and supporting non-functional tumor angiogenesis inhibits tumor growth." (PMID 33260925, 2020). "Apart from low oxygen, sevoflurane itself has been shown to induce HIF-1α in tumour cells.However, this increase of PD-L1 occurs simultaneously with a numerical depletion of TAMs from the TME." (PMID 32470095, 2020). "Remarkably, the HIF-1A/GLUT1/EMT axis correlates with not only the cold tumour immune status but also chemoradiation therapy, cancer aggressiveness and poor prognosis." (PMID 32238919, 2020). "We also observed the upregulation of HIF-1α expression, a marker of tumor hypoxia, in relapsed tumors after chemotherapy." (PMID 32630838, 2020). "The hypoxia microenvironment induces endogenous expression of H19 via Hif-1α, which directly binds to the H19 promoter, triggering the oncogenic effects in tumor cells." (PMID 32283739, 2020). "HIF-1α-related hypoxic pathways, NF-κB signalling pathways and cytokine-related pathways were upregulated in tumour treated with anti-VEGF antibody." (PMID 31932754, 2020). "In another study from the same group, tumor-infiltrating MDSCs expressed an increased level of miR-210 as compared with splenic MDSCs, and hypoxia induced miR-210 in splenic MDSCs via HIF-1α." (PMID 32793192, 2020). "A study performed with 91 patients showed that individuals with higher levels of HIF-1α in tumor histological samples -obtained surgically- had significantly shorter overall survival rates and disease-free periods than those with lower levels." (PMID 33135539, 2020). "It was shown that HIF-1α directly increased PD-L1 gene expression in MDSCs, macrophages, dendritic cells, and tumor cells." (PMID 33327450, 2020). "Herein we show using an autochthonous ccRCC model that Hif1a is essential for tumour formation whereas Hif2a deletion has only minor effects on tumour initiation and growth." (PMID 32807776, 2020). "The hypoxia-inducible factor (HIF)-1α was detected in the entire tumor mass of c-TOM models, and particularly in central tumor areas in h-TOM models." (PMID 33344431, 2020). "Lastly, even between L2HGDH and HIF1A loci, 14q was found to have several other yet-to-be-characterized potential ccRCC tumor-suppressors." (PMID 33077781, 2020). "HIF1α induced by the hypoxic TME up‐regulates downstream SDF‐1α to promote tumour proliferation and metastasis." (PMID 32588948, 2020).
tumor (continued). "Remarkably, the mRNA binding protein ELAV-like protein 1 (HuR), a key upstream modulator of HIF-1α and other targets, is also overexpressed in these tumor contexts." (PMID 32413989, 2020). "Conversely, the induction of SIRT3 was able to efficiently reduce tumor proliferation via an anti-Warburg effect mediated by the HIF1α/PDK1/PDHA1 pathway." (PMID 32138158, 2020). "Previous studies have demonstrated that the hypoxia-induced ROS/HIF-1α pathway plays important roles in tumor angiogenesis and VM formation." (PMID 32499699, 2020). "In fact, the presence of a low ADC mean value less than 1000 s2/m and the presence of p-mTor and HIF-1α hyperexpressions are warranted a tumor response or at least a stabilized disease." (PMID 33092063, 2020). "In this review, we have described the reciprocal regulation between HIF-1α and ncRNAs in terms of transcription, translation, and protein stability, as well as their effects on the various biological behaviors of tumor cells." (PMID 32014012, 2020). "HIF1α is considered the fundamental initiator of tumor angiogenesis, which initiates the process through regulating the key angiogenic factor vascular endothelial growth factor A (VEGFA) via a hypoxia-response element (HRE) present in the VEGFA promotor." (PMID 32545251, 2020). "We also show that eMIONs act as a nanozyme and have enhanced catalase-like activity in the presence of an alternative magnetic field, leading to tumor angiogenesis inhibition with a corresponding sharp decrease in the expression of HIF-1α." (PMID 33110072, 2020). "Activated PKC-δ causes angiogenesis and tumor growth of prostate tumors by increasing NADPH oxidase activity and HIF-1α expression levels." (PMID 32848510, 2020). "Differences were analyzed in the expression of vascular endothelial growth factor receptor‐2 (VEGFR2) and the number of Foxp3+ Tregs and hypoxia‐inducible factor (HIF)‐1α+ cells in tumor tissues sampled at the first and second (recurrence) surgeries." (PMID 32267594, 2020). "Next, we wondered why HIF1α or HIF2α knockout alone was unable to substantially decrease the tumour volume." (PMID 33208727, 2020). "Among the tissues, high expression of both HIF-1α and Nur77 appeared in the tumor tissues of three patients (numbers 1, 2 and 5) compared with adjacent tissues." (PMID 33245358, 2020). "Of these, HIF-1α is found to be constitutively expressed in many tumor cells, whereas the expression of HIF-2α and HIF-3α is restricted to certain tissues only." (PMID 33028364, 2020). "Hypoxia promotes cell invasion, tumor metastasis, and epithelial–mesenchymal transition by mediating the HIF-1α–MTDH loop in HNSCC cells." (PMID 33003428, 2020). "TEM also promote angiogenesis and tumor progression in hypoxic environment, through upregulation of HIF1α." (PMID 32775327, 2020). "On the one hand, receptor for advanced glycation end products (RAGE) binding to KRAS fuels the activation of HIF-1α and promotes tumor development and glycolysis in PDAC under hypoxia." (PMID 33256814, 2020). "Remarkably, HIF-1α impacts two of the more essential processes for tumor development and progression, angiogenesis and metabolism." (PMID 32751958, 2020). "ccRCC tumour cell lines frequently display intragenic deletions of HIF1A but express wild-type (WT) HIF-2α22." (PMID 32807776, 2020). "On the other hand, in both tumor models, we found a significant and similar decrease of HIF1-α in tumor samples from animals treated with Cy alone or with Cy+Los." (PMID 32850009, 2020). "Intratumoral hypoxia and alterations of the tumor microenvironmentare mechanisms that increase HIF-1α levels in breast cancer." (PMID 33680952, 2020). "Microvessel density and lumen formation assay confirmed that the pro-angiogenic ability of tumor cells was restored to some extent after reverse over-expression of HIF-1α." (PMID 32796813, 2020).